SLC2A3 (solute carrier family 2 member 3)
Diseases named in the same sentence as SLC2A3 in open-access papers (continued):
Sharing a sentence is not in itself a finding about the gene and the disease.
COVID-19 (4 papers, 2021 to 2024). A disease caused by infection with severe acute respiratory syndrome coronavirus 2. "We found that SLC2A3 (GLUT3) was increased in macrophage clusters enriched in severe COVID-19 patients." (PMID 34239034, 2021). "We found that expression of SLC2A3, which can be imaged by [18F]fluorodeoxyglucose, was higher in macrophages from severe COVID-19 patients." (PMID 34239034, 2021). "Notably, SLC2A3 (GLUT3) was highly expressed in macrophages enriched in severe COVID-19 patients." (PMID 34239034, 2021). "COBL, GPX3 and SOCS3 were lower in the early and late secretory phase in women with COVID-19, whereas DOCK2 and SLC2A3 were unchanged." (PMID 38372528, 2024). "This in silico model predicted that five genes important for embryo implantation were affected by COVID-19 (down-regulation of COBL, GPX3 and SOCS3, and up-regulation of DOCK2 and SLC2A3)." (PMID 38372528, 2024). "It is notable that SLC2A3 (GLUT3) was selected in this analysis, and this result indicates that it is a good candidate for targeted imaging reflecting immune cells in severe COVID-19 patients." (PMID 34239034, 2021). "Regarding alleged imaging markers, SLC2A3 was abundant in macrophage subtypes enriched in severe COVID-19 patients, and we identified SLC3A2, SLC2A3, and FOLR2 as candidate molecules as imaging targets." (PMID 34239034, 2021). "Among them, SLC2A3 and FPR1 demonstrated high expression in the severe COVID-19 in PBMC samples." (PMID 34239034, 2021). "SLC3A2 and SLC2A3 in the M01 cluster and FOLR2 in the M03 cluster were identified in results from both methods, indicating that [18F]FDG and [18F]-labeled folic acid derivatives may be useful for imaging severe COVID-19." (PMID 34239034, 2021).
Obesity (4 papers, 2018 to 2024). Accumulation of substantial excess body fat. "And, SLC2A3 was also on the top 10 hypo-methylated gene list in Cancer/control pair comparison, which suggested some association of obesity and CRC." (PMID 29876008, 2018). "Decreased expression of Slc2a3 was observed in the cardiac tissue of HFD mice, indicating dysregulated myocardial glucose transport in response to obesity." (PMID 32610475, 2020).
papillary thyroid cancer (4 papers, 2019 to 2021). "Another study has described the high expression of SLC2A3 in patients with papillary thyroid carcinoma, which is closely related to increased mortality." (PMID 33173535, 2020).
brain cancer (3 papers, 2019 to 2023). A primary or metastatic malignant neoplasm affecting the brain. "provided evidence that SLC2A3 can promote metastasis property of brain cancer cell and cAMP-response element binding protein (CREB) can directly regulate SLC2A3 expression." (PMID 34211835, 2021).
breast invasive carcinoma (3 papers, 2021 to 2022). "In the Curtis dataset, SLC2A3 mRNA expression was observed 2.665-fold decrease in invasive lobular breast carcinoma samples, while SLC2A4 downregulation was found in invasive breast carcinoma samples with a fold change of 5.226 from TCGA Breast dataset." (PMID 34488531, 2021). "The results showed that the expression level of SLC2A1 were higher in breast invasive carcinoma than in pairing normal tissues, and the expression levels of SLC2A3 and SLC2A4 were significantly lower in breast invasive carcinoma than in pairing normal tissues." (PMID 34525987, 2021).
dementia (3 papers, 2017 to 2022). Loss of intellectual abilities interfering with an individual's social and occupational functions. "This case–control study involved the Japanese cohort population to determine the association between VC transporter genes (SLC23A2, SLC2A1, and SLC2A3) and APOE4-associated risk of developing cognitive decline (MCI or dementia)." (PMID 34780525, 2021).
Huntington disease (3 papers, 2014 to 2022). Huntington disease (HD) is a rare neurodegenerative disorder of the central nervous system characterized by unwanted choreatic movements, behavioral and psychiatric disturbances and dementia. "In addition to CAG repeats in HTT, increased copy number of SLC2A3 can increase the level of GLUT3, therefore, delaying the age onset of Huntington’s disease." (PMID 36846102, 2022).
ischemic stroke (3 papers, 2019 to 2024). A stroke disorder caused by obstruction of blood flow to the brain, due to thrombotic (local blood clot formation) or embolic (due to a blood clot or other material traveling from another site) event. "Neuronal damage mitigation by modulation of SLC2A3 may be an effective therapeutic strategy that would benefit individuals who suffer from or are at high risk for ischemic stroke." (PMID 37386280, 2023). "Based on the adaptive upregulation of SLC2A3 under hypoxia and glucose-deficient conditions, it may be applied to the early diagnosis and target intervention of ischemic stroke." (PMID 37386280, 2023). "Since SLC2A3 has the best diagnostic effect, therefore, we further explored the biological role of SLC2A3 in ischemic stroke." (PMID 37386280, 2023). "In addition, SLC2A3 can affect neuroinflammation after ischemic stroke by influencing the conversion of CD4T cells to Treg cells." (PMID 37386280, 2023).
rheumatoid arthritis (3 papers, 2014 to 2019). A chronic, systemic autoimmune disorder characterized by inflammation in the synovial membranes and articular surfaces. "We genotyped the SLC2A3 copy number variant in four independent cohorts of rheumatoid arthritis and controls and one cohort of multiple sclerosis and controls." (PMID 30997344, 2019). "An overt disease phenotype of SLC2A3 copy number variants has not been reported; however, deletion of SLC2A3 has been previously reported to protect carriers from rheumatoid arthritis, implicating GLUT3 as a therapeutic target in rheumatoid arthritis." (PMID 30997344, 2019). "The frequency of the SLC2A3 copy number variant is not different between rheumatoid arthritis, multiple sclerosis and control groups." (PMID 30997344, 2019). "A replicated case–control study showed deletion of SLC2A3 was strongly protective against rheumatoid arthritis (odds ratio 0.442), and it was suggested that the role of GLUT3 as a GLUT in B cells and chondrocytes may provide a biological basis for this observation." (PMID 24452335, 2014).
Stroke (3 papers, 2022 to 2025). Sudden impairment of blood flow to a part of the brain due to occlusion or rupture of an artery to the brain. "In this study, we analyzed the expression of DUSP1, NCOA4 and SLC2A3 at 3, 5 and 24 h after stroke based on the GSE58294 dataset." (PMID 37699956, 2023).
testicular germ cell tumor (3 papers, 2021 to 2023). A germ cell tumor arising from the testis. "Indeed, previous studies showed that patients with testicular germ cell tumors may benefit from doxorubicin treatment in clinical trials, and future clinical trials may be warranted to test doxorubicin in treating subgroups of patients with tumors expressing elevated SLC2A3." (PMID 37523060, 2023).
abdominal aortic aneurysm (2 papers, 2020 to 2024). Enlargement and ballooning of the vessel that supplies arterial blood to the abdomen, pelvis and legs. "We obtained six macrophage hub genes (IL-1B, CXCL1, SOCS3, SLC2A3, G0S2, and CCL3) that can effectively diagnose abdominal aortic aneurysm." (PMID 38867262, 2024).
acute lymphoblastic leukemia (2 papers, 2015 to 2025). Leukemia with an acute onset, characterized by the presence of lymphoblasts in the bone marrow and the peripheral blood. "A recent publication indicated an inverse correlation between CDK6 and the prominent glucose transporter GLUT3/SLC2A3 expression levels in acute lymphoid leukemia patient samples." (PMID 39966356, 2025).
acute myocardial infarction (2 papers, 2024 to 2025). Necrosis of the myocardium, as a result of interruption of the blood supply to the area. "ROC curves of 5 differentially ferroptosis-related genes associated with myocardial infarction showed that SLC2A3, EPAS1, HMOX1, ATM and FANCD2 genes had good diagnostic value for myocardial infarction, and the area under the curve had statistical significance (P < 0.05)." (PMID 38253721, 2024). "ROC curves of 5 different genes related to ferroptosis associated with myocardial infarction showed that SLC2A3, EPAS1, HMOX1, ATM and FANCD2 genes had good diagnostic value for myocardial infarction, and the elevation of SLC2A3, EPAS1 and HMOX1 was a risk factor for myocardial infarction." (PMID 38253721, 2024). "In acute myocardial infarction, involving hypoxia and energy disruption, SLC2A3 expression correlates with metabolic changes during AMI." (PMID 40672380, 2025). "DBN1 and SLC2A3 are the final hub genes identified in our analysis, and they show potential as candidate biomarkers for the early diagnosis of acute myocardial infarction." (PMID 40672380, 2025). "The increase of SLC2A3, EPAS1 and HMOX1 were risk factors for myocardial infarction, while ATM and FANCD2 were protective factors." (PMID 38253721, 2024). "SLC2A3, EPAS1, HMOX1, ATM and FANCD2 genes all had good diagnostic value for myocardial infarction (P < 0.05)." (PMID 38253721, 2024). "Elevated expression levels of RAC1, IQGAP1, MYL6, DBN1, SLC2A1 and SLC2A3 were observed in acute myocardial infarction patients compared to healthy controls, suggesting a strong association with disease progression and indicating their potential as novel therapeutic targets." (PMID 40672380, 2025). "The increase of SLC2A3, EPAS1 and HMOX1 are risk factors for myocardial infarction, while ATM and FANCD2 are protective factors.Decision tree analysis showed that SLC2A3, HMOX1, ATM, FANCD2 gene had higher net yield in diagnosing myocardial infarction." (PMID 38253721, 2024). "The results showed that SLC2A3, HMOX1, ATM and FANCD2 genes had higher net yield in the diagnosis of myocardial infarction." (PMID 38253721, 2024). "According to the method of systematic random sampling, the sample size was divided into test set and verification set, and the decision tree model of SLC2A3, EPAS1, HMOX1, ATM and FANCD2 genes on myocardial infarction was established." (PMID 38253721, 2024).
atopic dermatitis (2 papers, 2020 to 2023). "While we were screening a molecular target for atopic dermatitis, we found the levels of glucose transporters including Glut1 (SLC2a1) and Glut3 (SLC2a3) are highly expressed in skin biopsies of dermatitis patients from multiple datasets." (PMID 31991554, 2020).
attention deficit-hyperactivity disorder (2 papers, 2024 to 2025). A disorder characterized by a marked pattern of inattention and/or hyperactivity-impulsivity that is inconsistent with developmental level and clearly interferes with functioning in at least two settings (e.g. at home and at school). "Copy number variants of SLC2A3 has been associated with attention deficit hyperactivity disorder and bipolar disorder." (PMID 40502709, 2025).
autoimmune disease (2 papers, 2014 to 2019). A disorder resulting from loss of function or tissue destruction of an organ or multiple organs, arising from humoral or cellular immune responses of the individual to their own tissue constituents. "Furthermore, given the tendency for autoimmune disorders to share susceptibility loci, and the role of SLC2A3 in the immune response, genetic variation in this region could also be important in other immune-related disorders." (PMID 24178905, 2014). "We also genotyped the SLC2A3 CNV in 450 families with autoimmune disease from the Multiple Autoimmune Disease Genetic Consortium (MADGC) to look for association with RA or autoimmune disease in general." (PMID 30997344, 2019).
bipolar disorder (2 papers, 2025). A disorder of the brain that causes unusual shifts in mood, energy, activity levels and the ability to carry out day-to-day tasks. "GLUT3 is encoded by the SLC2A3 gene, and copy number variants of SLC2A3 have been linked to various neuropsychiatric disorders, including attention deficit hyperactivity disorder (ADHD) and bipolar disorder." (PMID 41441197, 2025).
breast tumors (2 papers, 2012 to 2023). "Specifically, SLC2A1, SLC2A6, SLC2A10, and SLC2A13 were significantly overexpressed, whereas SLC2A3, SLC2A4, SLC2A9, SLC2A11, and SLC2A12 had downregulated expressions in breast tumors compared with those in normal breast epithelium." (PMID 37108300, 2023).
chronic thromboembolic pulmonary hypertension (2 papers, 2021). Chronic thromboembolic pulmonary hypertension (CTEPH) is characterized by the persistence of thromboemboli in the form of organized tissue obstructing the pulmonary arteries. "In particular, the researchers identified circ_0022343-miR-503-5p-solute carrier family 2 member 3 (SLC2A3) for the potential regulation of eosinophils in chronic thromboembolic pulmonary hypertension." (PMID 34445627, 2021). "Solute carrier family 2 member 3 (SLC2A3) is reported to correlate with platelet aggregation, syndromic congenital heart disease, and chronic thromboembolic pulmonary hypertension." (PMID 34957234, 2021).
cognitive decline (2 papers, 2021 to 2024). "We hypothesized that genetic variants of VC transporters (SLC23A2, SLC2A1, and SLC2A3) expressed in the brain could affect the risk of developing APOE4-associated cognitive decline." (PMID 34780525, 2021). "In the present study, we aimed to examine the effects of functional variants of VC transporter genes expressed in the brain (SLC2A1, SLC2A3, and SLC23A2) on APOE4-associated risk of developing cognitive decline." (PMID 34780525, 2021). "To investigate the relationship between cognitive decline and brain VC level in humans, we need to focus on the roles of brain-expressed VC transporters (SLC23A2, SLC2A1, and SLC2A3) in human cognitive function." (PMID 34780525, 2021).
congenital heart disease (2 papers, 2021 to 2023). A heart disease that is present at birth. "Mutations affecting the solute carrier family 2 member 3 (SLC2A3) gene, located on chromosome 12p13.31, have been linked to congenital syndromic heart defects, although the molecular mechanisms still remain elusive." (PMID 37239976, 2023).
dermatitis (2 papers, 2020 to 2023). An inflammatory process affecting the skin. "We determined the expression levels of glucose transporters Glut1 (SLC2a1) and Glut3 (SLC2a3) in skin biopsies of dermatitis patients and control subjects from several datasets." (PMID 31991554, 2020).
esophageal cancer (2 papers, 2022 to 2023). A primary or metastatic malignant neoplasm involving the esophagus. "For instance, LINC00667 stimulates migration, invasion, and proliferation in cells pertaining to esophageal cancer by mediating the sponge axis miR-200b-3p/SLC2A3." (PMID 37827696, 2023).
glaucoma (2 papers, 2015 to 2023). Increased pressure in the eyeball due to obstruction of the outflow of aqueous humor. "ROC curves suggested that miR-106-5p-CAPZA2/CREB1 axis and miR-15a-5p-SLC2A3 axis (AUC > 0.9) exhibited excellent ability to distinguish POAG from non-glaucoma individuals." (PMID 37940950, 2023).
Hypertension (2 papers, 2019 to 2020). The presence of chronic increased pressure in the systemic arterial system. "Our search revealed both known KDs showing connections to hypertension or relevant conditions in one or more types of studies (99 KDs; such as GNAS, SLC2A3, IRS1, ADM, and SERPINE1) and relatively novel KDs in BP studies (such as SPTBN1 and GNB1)." (PMID 30931314, 2019).
hyperthyroidism (2 papers, 2022 to 2024). Overactivity of the thyroid gland resulting in overproduction of thyroid hormone and increased metabolic rate. "As a link to increased energy demands with hyperthyroidism, we checked the expression of Slc2a1, Slc2a3 and Slc2a4 encoding for class I glucose transporters GLUT1, GLUT3 and GLUT4, respectively, that facilitate glucose transport across the cell membrane." (PMID 38719881, 2024).
multiple myeloma (2 papers, 2022). "Of the 13 members of the Slc2 family in mice, primary plasma cells and/or myeloma cells expressed SLC2A3, SLC2A6, and SLC2A8 as candidate glucose transporters in addition to SLC2A1." (PMID 36001583, 2022).
oral cancer (2 papers, 2024 to 2025). "SLC2A3 plays a crucial role in oral cancer development by facilitating glucose transport across cell membranes, thus supporting the enhanced glycolytic activity necessary for rapid tumor cell proliferation." (PMID 38625978, 2024). "This study first assessed the expression of SLC2A3 in oral cancer tissues and cells." (PMID 38625978, 2024). "Interestingly, exogenous lactic acid restored the EMT, proliferation, migration, and invasion abilities of oral cancer cells inhibited by knocking down SLC2A3." (PMID 38625978, 2024).
osteoarthritis (2 papers, 2022 to 2024). A noninflammatory degenerative joint disease occurring chiefly in older persons, characterized by degeneration of the articular cartilage, hypertrophy of bone at the margins and changes in the synovial membrane. "The classification model constructed by LASSO analysis showed that six genes including CDKN1A, FOSB, STMN2, SLC2A3, TAC, and SCRG1 can be used as biomarkers of osteoarthritis, and the SCRG1 gene shows importance in osteoarthritis." (PMID 35720295, 2022).
periodontitis (2 papers, 2022 to 2025). An acute or chronic inflammatory process that affects the tissues that surround and support the teeth. "The role of overexpressed SLC2A3 in neutrophil ferroptosis during periodontitis should be further explored." (PMID 36686646, 2022). "This study found overexpression of SLC2A3 in neutrophil infiltrated in periodontal tissue during periodontitis." (PMID 36686646, 2022). "This is the first bioinformatics report describing the upregulation of necroptosis (IL-1B), pyroptosis IL-1B, TREM1, and FPR2, and ferroptosis (SLC2A3) related genes mainly in human periodontium infiltrated neutrophils during periodontitis." (PMID 36686646, 2022). "The role of SLC2A3 in periodontitis pathogenicity and periodontitis-associated cell death has not been reported so far." (PMID 36686646, 2022). "Discussion: The findings provide upregulated SLC2A3, FPR2, TREM1, and IL1B in neutrophils as a future research direction on the mode and mechanism of cell death in periodontitis and their role in disease pathogenicity." (PMID 36686646, 2022). "We found that among 21 DCDEGs, SLC2A3, FPR2, TREM1, and IL1B were mainly upregulated in neutrophils present in the periodontium of periodontitis patients." (PMID 36686646, 2022). "In conclusion, our study showed that SLC2A3, FPR2, TREM1, and IL1B mainly upregulated in neutrophils infiltrated in periodontium during periodontitis." (PMID 36686646, 2022). "The scRNA sequencing data analysis revealed that among 21 DCDEGs, SLC2A3, FPR2, TREM1, and IL1B were mainly upregulated in neutrophils present in the periodontium of periodontitis patients." (PMID 36686646, 2022). "The rigorous bioinformatics analysis performed in this study provided hints that SLC2A3, FPR2, TREM1, and IL1B are upregulated in neutrophils infiltrated in periodontium during periodontitis and mainly attributed to necroptosis, pyroptosis, and ferroptosis." (PMID 36686646, 2022).
placental insufficiency (2 papers, 2013 to 2020). Failure of the placenta to deliver an adequate supply of nutrients and oxygen to the fetus. "In the present study, placental insufficiency could be explained, at least in part, by decreased placental mRNA expression of SLC2A3, a gene encoding a glucose transporter, GLUT-3, although mRNA expression of SLC2A1, which encodes for GLUT-1, did not change by ET." (PMID 33244103, 2020).
renal cell carcinoma (2 papers, 2020 to 2022). "Similarly, upregulation of SLC2A3 could enhance CD28 costimulation reprogrammed renal cell carcinoma CD8+ TIL metabolism, which is antagonized by the inhibitory and checkpoint immunotherapy receptors CTLA4 and PD-1." (PMID 36247875, 2022).